SNORD115-14 (small nucleolar RNA, C/D box 115-14)
Synonyms: HBII-52-14
Gene: Small nucleolar RNA gene on chromosome 15 (25,194,921 to 25,195,001, forward strand). Ensembl gene ENSG00000199960.
Gene Ontology:
Biological process: RNA processing
Cellular component: nucleolus
Homologues: Paralogues in human: SNORD115-10 (99% identical), SNORD115-12 (99% identical), SNORD115-42 (99% identical), SNORD115-9 (99% identical), SNORD115-11 (98% identical), SNORD115-13 (98% identical), SNORD115-15 (98% identical), SNORD115-20 (98% identical), SNORD115-21 (98% identical), SNORD115-29 (98% identical), SNORD115-36 (98% identical), SNORD115-39 (98% identical), and 37 more.